EPCAM (epithelial cell adhesion molecule)
Diseases named in the same sentence as EPCAM in open-access papers (continued):
Sharing a sentence is not in itself a finding about the gene and the disease.
metastatic carcinoma (28 papers, 2011 to 2025). A carcinoma which has spread from the original site of growth to another anatomic site. "In six other bone marrow aspirates from five patients, immunocytochemistry revealed metastatic carcinoma cells positive for cytokeratins and BerEP4/EpCAM." (PMID 39907157, 2025). "Analysis of EpCAM expression on CTCs isolated from metastatic carcinoma patients demonstrated a mean expression of around 50,000 EpCAM molecules per cell." (PMID 36613466, 2022). "Several PDAC CTC cell lines isolated from patients with metastatic cancer were first probed for the expression of surface EpCAM by labeling cells with PE-conjugated anti- EpCAM antibodies." (PMID 36009530, 2022). "Since then, a clinical trial has been recruiting patients with various metastatic cancers to measure CTC levels when enriched with membranous heat shock protein (mHSP70) vs EpCAM (NCT04628806)." (PMID 35749519, 2022). "In these results, EpCAM shows significantly increased expression in the metastatic stage of cancer compared with primary tumors, indicating that EpCAM is a potential therapeutic target for metastatic cancer." (PMID 34790117, 2021). "The detection of CTCs as defined by the EpCAM+/CK+/DAPI+/CD45− expression pattern has been observed in the blood of metastatic cancer patients, including mBC, and their relevance affecting metastatic competence has been established." (PMID 34638368, 2021). "In comparison, an increasing trend was observed in the number of CTCs captured from patients with metastatic cancer using anti-EpCAM antibodies." (PMID 34567635, 2020). "Using this approach, we intercalated doxorubicin (DOX) into a bifunctional aptamer targeting the transferrin receptor on the BBB and epithelial cell adhesion molecule (EpCAM) on metastatic cancer cells." (PMID 32027209, 2020). "The ldEVs had a similar size range to our previously reported DAPI-, CD45-, CK+ tumor-derived Extracellular Vesicles (tdEVs), that were detected after EpCAM enrichment in metastatic cancer patients." (PMID 31434250, 2019). "Presence of ldEVs and leukocytes in image data sets of EpCAM-enriched samples of 25 healthy individuals and 75 metastatic cancer patients was evaluated using the ACCEPT software." (PMID 31434250, 2019). "These two findings have important implications for our previously reported tumor-derived Extracellular Vesicles (tdEVs), that were immunomagnetically co-isolated with CTCs based on their EpCAM expression from metastatic cancer patients." (PMID 31434250, 2019). "The epithelial cell adhesion molecule (EpCAM), which is involved in intercellular adhesion of epithelial cells and signal transduction, is frequently overexpressed in primary and metastatic cancer." (PMID 30424286, 2018). "We first screened a large panel of markers, including EpCAM, for more effective isolation of CTCs from the peripheral blood of patients with metastatic cancer." (PMID 27711186, 2016). "Duplicate tubes of blood from metastatic cancer patients were incubated with anti-EpCAM only and with the antibody mixture." (PMID 21577258, 2011). "The cell cluster C1, classified as Epithelial Cell Adhesion Molecule (EpCAM)+ metastatic cancer cell and correlated with activation of tight junction and adherence junction, was significantly enriched in the recurrent MPE group, in which Claudin‐4 (CLDN4) was identified." (PMID 38629624, 2024). "Several studies have shown that anti-EpCAM antibodies limit therapeutic efficacies as the results of showing dose- and target-dependent in metastatic cancers, short serum half-life, altered EpCAM expression pattern, and differential cleavage and localization of EpICD in cancer cells." (PMID 35986321, 2022). "Among the isolated CTCs, EpCAM+ CTCs were only detected in patients with metastatic cancer." (PMID 32764280, 2020). "EpCAM is also overexpressed on the surface of the majority of primary and metastatic cancers." (PMID 32764280, 2020).
metastatic carcinoma (continued). "Using EpCAM targeted MBs CTCs from metastatic cancer patients were isolated, suggesting that this technique could be developed into a valuable clinical tool for isolation, enumeration and analysis of rare cells." (PMID 23516425, 2013). "Owing to its frequent and high expression on carcinomas and their metastases, EpCAM serves as a prognostic marker, a therapeutic target, and an anchor molecule on circulating and disseminated tumor cells (CTCs/DTCs), which are considered the major source for metastatic cancer cells." (PMID 32507912, 2020). "Results revealed a higher Mesenchymal markers in primary cancer cells (e.g., NCAM1, LAMB1, SERPINE1, TCF4, VIM, ZEB1, and ZEB2) and a higher Epithelial markers in metastatic cancer cells (e.g., CDH1, CLDN4, ELF3, EPCAM, KRT18, KRT7, and KRT8)." (PMID 37202394, 2023). "Using this method, blood is taken from subjects with metastatic cancer, processed by exclusion of CD45 + cells and capturing of EpCAM + cells in the VERSA, and stained for Hoechst, cytokeratin, and exclusion markers (CD11b, CD45, CD14, CD34)." (PMID 32255253, 2020). "Comparison of CTCs isolated by CellSearch or magnetic beads coated with anti-EpCAM, anti-EGFR or anti-FGFR from patients with metastatic cancer." (PMID 27711186, 2016). "In fact, not all tumor types express EpCam and the EpCam expression can be lost during the epithelial-to-mesenchymal transition in metastatic cancers." (PMID 36815877, 2023). "Moreover, the mean DTC number per patient was six times higher and the percentage of EpCAM+ DTCs was significantly higher in patients with metastatic cancer than in patients without metastases (66.53% vs. 8%)." (PMID 32764280, 2020). "Taking into account that EpCAM-positive CTCs isolated from patients with metastatic cancer present a hybrid epithelial-mesenchymalphenotype, we might suppose that an EpCAM-negative population will express EMT markers at a higher rate." (PMID 27711186, 2016).
Cirrhosis (27 papers, 2012 to 2025). A chronic disorder of the liver in which liver tissue becomes scarred and is partially replaced by regenerative nodules and fibrotic tissue resulting in loss of liver function. "Based on the notion that EpCAM serves as a marker of normal hepatic stem cells, researchers sought the mechanism of tumorigenicity of EpCAM in the pre-cancerous stage of advanced cirrhosis." (PMID 38455361, 2023). "Investigations into EpCAM + cells from advanced cirrhosis revealed an elevated expression of the Notch gene, accompanied by enhanced self-renewal in-vitro and an increased resemblance to HCC regarding genetic products." (PMID 38455361, 2023). "In conclusion, we report the existence of a small population of EpCAM+ CSC like cells in advanced cirrhosis, which have the potential to develop into HCC because of their limitless self‐renewal through autocrine activation of Wnt signaling." (PMID 28176469, 2017). "Flow cytometric analysis also showed an increase in number of EpCAM+ cells in advanced cirrhosis as compared to histologically normal tissue specimens." (PMID 28176469, 2017). "Both flow cytometry and immunohistochemistry showed that frequency of EpCAM+ cells in advanced cirrhosis was increased as compared to control." (PMID 28176469, 2017). "IHC in cirrhosis revealed that EpCAM expression was increased particularly near the periportal areas in the bile ductules, oval cells, and intermediate hepatocytes." (PMID 28176469, 2017). "NGS revealed that Wnt signaling was regulated by genes and miRNAs commonly expressed by EpCAM+ cells of both advanced cirrhosis and HCC." (PMID 28176469, 2017). "Nevertheless, it is reasonable to conclude from this result that EpCAM+ cells from advanced cirrhosis include a subset of CSCs." (PMID 28176469, 2017). "In accordance with these reports, we too observed increased expression of EpCAM+ cells near the ductular regions of advanced cirrhosis liver sections." (PMID 28176469, 2017). "We observed an increase in the number of EpCAM+ cells during advanced cirrhosis, warranting further studies to delineate if they have any similarity with CSCs." (PMID 28176469, 2017). "EpCAM+ cells in advanced cirrhosis possibly include a population of CSC‐like cells which can be explored for early diagnosis of HCC development." (PMID 28176469, 2017). "FGF19, FGFR4 and EpCAM expressions between the different histologic stages of fatty liver steatohepatitis-cirrhosis-HCC carcinogenesis sequence were compared to healthy hepatic tissue." (PMID 27447573, 2016). "In addition, epithelial cell adhesion molecule (EpCAM) overexpression has been observed during liver development, regeneration and following the recovery from cirrhosis." (PMID 31827403, 2019). "Human cirrhotic and cirrhosis-associated HCC tissues showed an increase of IMP2 expression and of the progenitor cell markers SOX9, SPP1/osteopontin, CDH1/E-cadherin, AFP, PROM1/CD133, BEX1, EPCAM." (PMID 31555647, 2019). "Therefore, we cultured the EpCAM+ cells from advanced cirrhosis and HCC patients in ultra‐low attachment plates with and without the Wnt inhibitor, IWP12." (PMID 28176469, 2017). "Since HCC mostly develops on a cirrhotic background, we sought to determine whether CSC‐like EpCAM+ cells exist in patients with advanced cirrhosis." (PMID 28176469, 2017). "In this study, CSC like EpCAM+ cells were observed in patients with advanced cirrhosis." (PMID 28176469, 2017). "High intratumoral EpCAM was significantly associated with more major vascular invasion (P = 0.023), high AFP (P < 0.001) and high Edmondson grade (P = 0.005), High intratumoral OV6 expression of the entire group demonstrated more cirrhosis (P = 0.015)." (PMID 25197550, 2014). "Maybe, EPCAM can be considered as a target of drug in the treatment of NAFLD of HCC with cirrhosis." (PMID 36397165, 2022).
Cirrhosis (continued). "Julich-Haertel and colleagues showed that the combination of annexin V+ EpCAM+ ASGPR1+ CD133+ taMPs allowed one to distinguish liver malignancies and cirrhosis." (PMID 36555854, 2022). "Number of spheroids formed by EpCAM+ cells isolated from both HCC and advanced cirrhosis increased exponentially at every passage." (PMID 28176469, 2017). "We therefore wanted to compare the level of expression of these genes in EpCAM+ cells isolated from control (Ep+NSC), advanced cirrhosis (Ep+CIR) and AFP+ HCC tissues (Ep+HCC)." (PMID 28176469, 2017). "The IHC results demonstrated significant increases of protein expressions of FGF19, FGFR4 and EpCAM in specimens with fatty liver, NASH, cirrhosis, and HCC compared to healthy liver tissue." (PMID 27447573, 2016). "Interestingly, up-regulated FGF19 signaling significantly correlated with epithelial cell adhesion molecule (EpCAM), one of biomarkers of EMT and stemness, following the steatosis-steatohepatitis-cirrhosis-HCC sequence." (PMID 29973237, 2018). "Taken together, these results suggest that EpCAM+ cells from advanced cirrhosis have limitless self‐renewal capacity unlike Ep+NSCs." (PMID 28176469, 2017). "In the present study, we therefore compared molecular and functional features of EpCAM+ cells from advanced cirrhosis, HCC and paired adjacent noncancerous/noncirrhotic (control) liver tissues along with EpCAM‐cells from the same HCC tissues (Ep‐HCC)." (PMID 28176469, 2017). "Some intermediate hepatocyte-like cells (IHLCs) adjacent to portal tracts from patients with cirrhosis showed immunopositivity for MMP-2 rather than EpCAM." (PMID 27881141, 2016). "Patients with a high peritumoral EpCAM and CD133 expression level were more prone to have high TNM stage, high Edmondson grade in patients with the high peritumoral OV6 expression, and high peritumoral c-kit expression patients demonstrated more cirrhosis." (PMID 25197550, 2014). "At present, EPCAM was a hub gene in PPI network and one of the top 10 DEGs, as well as Hyper-LG, in NAFLD HCC patients with cirrhosis, which indicated that EPCAM may exert a momentous role in inflammatory response and tumorigenesis in NAFLD of HCC with cirrhosis." (PMID 36397165, 2022). "Although CTCs are either not detected or are extremely rare in healthy individuals or patients with benign conditions, there is no sufficient data to describe the incidence of circulating EpCAM-positive epithelial cells commonly associating HCC,as liver injury, cirrhosis, or viral hepatitis." (PMID 32212818, 2020). "Meanwhile, annexinV+ EpCAM+ ASGPR1+ CD133+ TMPs can distinguish HCC, CCA, and cirrhosis patients from those without tumors." (PMID 38665948, 2024). "Compared to non-NAFLD of HCC patients with cirrhosis, GNG4, EPCAM, SPARCL1, DGKK, and SLC39A4 were down-regulated and HOXD9 was up-regulated in NAFLD of HCC patients with cirrhosis." (PMID 36397165, 2022).
ovarian tumors (27 papers, 1994 to 2025). "In the co-culture of adherent EpCAM-positive ovarian tumor cells, which highly expressed FOLR1, with autologous PBL from patient #1, stimulation with ETA-067 and rIL-2 induced enhanced lysis (90%) of the tumor cells." (PMID 40755782, 2025). "We analyzed the evolution of the abundance of CD117 and EpCam markers on EVs in the course of the development of post-treatment relapsed ovarian tumor." (PMID 36875773, 2023). "In parallel, the absolute cell number of viable EpCAM (CD326)-positive ovarian tumor cells is reduced compared to day 0, which underline the observation that Vδ2 T-cell cytotoxicity is not influenced by galectin-3." (PMID 38259448, 2023). "The present work aimed at analyzing the abundance of mesenchymal marker CD117 and epithelial cell adhesion molecule (EpCam) on the surface of extracellular vesicles derived from ovarian tumors." (PMID 36875773, 2023). "PD‐L1 expression was decreased in EpCAM‐positive tumor cells from ascites and ovarian tumors in the PF543‐treated mice compared to the controls." (PMID 35289120, 2022). "The epithelial cell adhesion molecule (EpCAM) is over-expressed on the surfaces of several cancer cells, including ovary tumors, and has been regarded as a marker for tumor diagnosis and therapy." (PMID 33917060, 2021). "We present the first case of ileum cancer in a patient with germline EPCAM gene deletion, which was discovered during ovarian tumor surgery." (PMID 32272879, 2020). "Here, we present the first case of ileum cancer in a patient with germline EPCAM gene deletion, which was discovered during ovarian tumor surgery." (PMID 32272879, 2020). "By using an in vivo limiting dilution assay, we found that EpCAM-positive cancer cells isolated from hierarchically organized ovarian tumors have greater tumor-initiating properties than EpCAM-negative cancer cells." (PMID 31261739, 2019). "In a limiting dilution assay, EpCAM-positive cancer cells isolated from hierarchically organized ovarian tumors showed highly tumorigenic properties in comparison with EpCAM-negative cells." (PMID 28574829, 2017). "We previously identified a subpopulation of EpCAM-positive cancer cells as candidates for CSCs in established mouse ovarian tumors generated by transduction of defined genetic alterations." (PMID 28574829, 2017). "Flow cytometric analysis revealed lower frequencies of CD44+ cells in ascites and a higher frequency of EpCAM+ cells in miliary ovarian tumors." (PMID 25991672, 2015). "Epithelial cell adhesion molecule (EpCAM) was found to be expressed in all COVCAR cell lines studied but not in NOSE cells suggesting the metastatic nature of the COVCAR cells and the use of EpCAM as a potential ovarian tumor marker." (PMID 23460878, 2013). "The role of EpCAM in ovarian tumour progression, however, is unclear; one study reported that FIGO stage III/IV showed lower EpCAM expression than stage I, while in another study, FIGO stage III/IV showed higher EpCAM expression than stage I/II disease." (PMID 21694727, 2011). "This phenomenon may be an additional explanation of the contradictory results of EpCAM overexpression in ovarian tumors in relation to its prognostic value." (PMID 37375854, 2023). "Research on EpCAM-specific EVs might also shed light on the contradictory results of the immunohistochemical evaluation of EpCAM overexpression in ovarian tumors in relation to its prognostic value, in terms of overall survival and response to chemotherapy." (PMID 37375854, 2023). "An increase in EpCAM expression was detected in metastatic tissue compared to primary ovarian tumors, which could eliminate the need to firstly immunohistochemically analyze primary tumors for target identification prior to surgery." (PMID 32545676, 2020).
ovarian tumors (continued). "In this regard, research successfully used anti-epithelial cell adhesion molecule (EpCAM) to isolate exosomes secreted from ovarian tumors in plasma and compared exosome-containing miRNA expression profiles between samples from cancer patients versus healthy controls." (PMID 24782983, 2014). "In that study, circulating tumor exosomes were isolated using an anti-EpCAM-modified MACS procedure, and the microRNA profile of ovarian tumors was compared with that of tumor exosomes isolated from the same patient." (PMID 35723400, 2022). "CD44 and CD24, along with epithelial cell adhesion molecule (EpCAM), have been successfully used to identify putative CSC population in ovarian tumors." (PMID 34207464, 2021). "Single-cell suspensions of fresh human ovarian tumours comprised both CD45+ cells and EpCAM+ cancer cells." (PMID 33402737, 2021). "The discoveries for the presence of microRNAs, EpCAM, and CD24 in ovarian tumor-derived exosomes have provided promising alternatives to early detection." (PMID 24460816, 2014). "If we consider EpCam as an exclusively epithelial marker and calculate the signal ratio CD117/EpCam, the difference between SK-OV-3 and MES-OV cell lines, as well as between primary and relapsed ovarian tumors, is more pronounced." (PMID 36875773, 2023). "Finally, CD44-EpCAM (Epithelial Cell Adhesion Molecule) aptamer is a double-stranded RNA adaptor which acts blocking both, CD44 and EpCAM, simultaneously reducing tumor progression and promoting apoptosis, both in vitro and in vivo xenograft models of ovarian tumor cells (OVCAR8)." (PMID 35785191, 2022). "The correlation analysis results also indicate that EpCAM and CLDN6 are only co-expressed in ovary tumor, but not in other tumors, such as stomach and Colorectal tumors." (PMID 40057807, 2025).